MMP2 (matrix metallopeptidase 2)
Diseases named in the same sentence as MMP2 in open-access papers (continued):
Sharing a sentence is not in itself a finding about the gene and the disease.
tumor (continued). "The probe was constructed by connecting the following 3 main parts: the homing peptide CREKA, which is capable of targeting the tumor stroma, the cell-penetrating peptide Tat, and a linker (PLGLAG) that can be cleaved by matrix metalloproteinase-2 and -9 (MMP-2/9)." (PMID 29686590, 2018). "MMPs, also considered as markers of epithelial-to-mesenchymal transition (EMT) (especially MMP-2 and MMP-9), render tumor cells able to metastasize in distant organs by breaking down the basement membrane, thus allowing cancer cells to enter the lymphatic or blood vessels." (PMID 30301152, 2018). "No expression of MMP-2 was seen close to the tumour-invaded area or in tumour-free parts of the peritoneal tissue." (PMID 29623449, 2018). "Moreover, TGF-β, released from TAMs, induces matrix metalloproteinase 2 (MMP-2) and 9 (MMP-9) expression from the tumor to enhance GSC invasion." (PMID 30577488, 2018). "Finally, immunohistochemistry results indicated that the expression levels of Snail, VE‐cadherin, MMP2 and HIF‐1α were reduced in tumours with TP53INP1 overexpression, and the expression of E‐cadherin was increased." (PMID 29655255, 2018). "The present study found that overexpression of MCPIP3 inhibited MMP-2 mRNA expression, indicating that MCPIP3 may inhibit MMP gene expression and thus tumor cell metastasis." (PMID 29751537, 2018). "Gelatinases MMP-2 and MMP-9 are responsible for Fibulin-2 degradation in these tumor cells." (PMID 28099917, 2017). "Given that ECM is the first vital barrier in the tumor invasion and metastasis process and the main component of ECM is type IV collagen, together with important role of MMP2 in degradation of type IV collagen, MMP2 is regarded as a key enzyme involved in invasion and metastasis of cancer." (PMID 28709407, 2017). "MMP2, MMP3, MMP9, uPA and Cathepsin B play critical roles in tumor invasion and metastasis." (PMID 29137230, 2017). "When the peptide substrate (GPLGIAGQ) incorporated on the surface of the NP is cleaved by MMP2, the PEG shield is released from the NP, enabling the multifunctional micelle particle containing siRNA and paclitaxel to interact with tumor cell surface and be imported into the cell." (PMID 29218233, 2017). "In consideration of the Shh and Gli-1 results, we can speculate that the decreased MMP-2 and MMP-9 levels may be due to the inhibited activity of the Hh signaling pathway by high intracellular DOX concentrations, thus inhibiting tumor invasion and migration." (PMID 29157266, 2017). "However, significant increase in TGF-β1, MMP-2 and MMP-9 gene expression was noted in tumor cells from high metastatic lesions in the lungs." (PMID 28819116, 2017). "Furthermore, we stained the intracranial tumours with IKBKE, YAP1, MMP-2, MMP-9, E-cadherin, N-cadherin, β-catenin, vimentin, and snail." (PMID 28548934, 2017). "Tumor suppressor miR-491-5p exerts its role in repressing OSCC metastasis by targeting Git1, which leads to the perturbation of FAK/paxilin and ERK1/2 signaling along with MMP2/9 expression and activity." (PMID 29206174, 2017). "Western blotting and immunohistochemical assays revealed the upregulation of invasion-related proteins MMP2 and MMP9, and proliferation-related protein Cyclin D1 in the CEP55-overexpressing tumour tissues, which coincided with the aggressive phenotype displayed by Capan-1/CEP55 cells." (PMID 28724890, 2017). "In terms of MMP-9 and MMP-2, both were not up-regulated by sorafenib and IFN-α, and other factors associated with tumor invasion and migration require further confirmation in our future research." (PMID 29100435, 2017).
tumor (continued). "In summary, these results indicate that MMP-2 and TIMP-1 possibly aided by c-MET may promote tumor progression by enhancing angiogenesis and tumor invasion." (PMID 28234925, 2017). "We also observed that MMP9 but not MMP2 was overexpressed in tumor parts (mean dCT of tumor vs. normal tissue: 1.30 vs. 3.43, p < 0.0001), and that increased MMP9 in early and advanced stages in 60 paired NSCLC tissues was correlated with MIAT." (PMID 29228680, 2017). "Further study is needed to identify the pro-invasive protein in cells with DM and the contribution of MMP2 to overall tumor growth and angiogenesis in cells without DM." (PMID 29113349, 2017). "Similar to both MMP-2 and c-MET, TIMP-1 positive cells were present around blood vessels as well as in areas of necrosis, and similar to MMP-2, cells expressing TIMP-1 were also observed in the tumor periphery." (PMID 28234925, 2017). "As expected, MMP2 was over-expressed in tumor samples compared to no-tumor samples (72.0% vs 22.6%, P < 0.001)." (PMID 28959024, 2017). "It has been shown that Ku80 could upregulate metalloproteinase (MMP)-2 and MMP-9 expression through activating ERK/JNK pathway, where MMPs correlate to angiogenesis, oncogenesis, tumor invasion and metastasis." (PMID 28399858, 2017). "Furthermore, rottlerin inhibits the markers of angiogenesis (COX-2, VEGF, VEGFR, and IL-8), and metastasis (MMP-2 and MMP-9), thus blocking production of tumorigenic mediators in the tumor microenvironment." (PMID 28423559, 2017). "CD147 and MMPs, especially MMP-2 and MMP-14, are frequently involved in tumor cell metastasis." (PMID 28881637, 2017). "While MMP2- and MMP9-deificent embryonic fibroblasts co-injected with SCCA cells demonstrated suppressed tumor growth in a mouse model of cancer, an enhancement of tumor establishment was noted, suggesting that CAF are sufficient, but not necessary, for tumor development." (PMID 28966935, 2017). "In another study, only a small sample of 49 patients was analyzed with the conclusion that MMP2 and MMP9 overexpression might be related to tumor kinetics but warrants further investigation." (PMID 29138529, 2017). "The levels of both MMP-2 and TIMP-2 expressions in tumors may facilitate the initiation and progression of multiple biological behaviors required for tumor progression." (PMID 26729052, 2017). "In addition to ECM, MMP2 and MMP9 can cleave cytokines, growth factors, chemokines and receptors of cytokines involved in tumor progression." (PMID 28620234, 2017). "Ln‐5 fragments cleaved by MMP‐2 contain an EGF‐like domain, and these fragments may bind to tumour EGFRs to activate downstream signalling pathways." (PMID 28766880, 2017). "This combination also down-regulated MMP-2, MMP-9, Shh and Gli-1 in tumor xenografts." (PMID 29157266, 2017). "The activation of the PI3K/Akt pathway may also upregulate the expression levels of MMP2 mRNA and protein and the degradation of various ECM components to promote tumour metastasis." (PMID 29228922, 2017). "There are five different classes of MMPs, and they include the gelatinases MMP-2 and MMP-9, that are overexpressed in neoplastic tissue, and are correlated with tumor aggressiveness and metastatic potential; MMPs are also potential targets for therapeutic interventions." (PMID 28846661, 2017). "Both MMP-2 and MMP-9 are mainly involved in tumor metastasis." (PMID 27073100, 2017). "A 2.4-fold higher internalization of the MMP2-sensitive formulation in tumor cells was achieved compared to the non-sensitive counterpart." (PMID 28335259, 2016). "Reduction in MMP2 and MMP9 expression after S100A8 and S100A9 knockdown in the cancer cells suggests their regulation by the S100 proteins, and is consistent with decreased tumor cell migration and invasion." (PMID 27086923, 2016).
tumor (continued). "MMP2 and MMP9, two members of the gelatinase subfamily of MMPs, are thought to particularly play a role in the early steps of cancer cell invasion and tumor vascularization since they cleave type IV collagen, laminin and elastin, which are the major components of the basement membrane (BM)." (PMID 27042827, 2016). "We found that knockdown of LGMN could downregulate the expression of MMP2 and MMP9, which could break down extracellular matrix and promote tumor metastasis." (PMID 27656894, 2016). "From the in vivo study it has been found that 21 could retard tumor growth of Hep3B xenograft models and reduced CD31 and MMP-2 expression in tumor tissues." (PMID 26880913, 2016). "The MAPK pathways are prominent mechanisms that coordinate the transcription factors, such as NF-κB and CREB, which are activated and phosphorylated by ERK and JNK kinase systems to regulate downstream MMP-2 and MMP-9 gene expression, subsequently increase tumor initiation and progression." (PMID 27144433, 2016). "The effects of HOXA11-AS on tumor progression may be mediated by genes involved in cell migration, invasion, and EMT-related genes; these genes include VEGF, MMP-9, MMP-2, E-cadherin, β-catenin, Vimentin, and Snail." (PMID 27792998, 2016). "Similarly, the decrease in MMP2/9 mRNA levels and the increase in CDH1 mRNA level were observed in tumor tissue using Real-time PCR analysis (the lowest panel, *P < 0.05, **P < 0.01, ***P < 0.001, vs control)." (PMID 26811493, 2016). "One of the EFEMP1 variants was identified as the sought-after ETSP, which had a stronger tumor-suppression function in TMCs by targeting EGFR and angiogenesis, and a new tumor-suppression function in STICs by targeting NOTCH signaling and MMP2-mediated cell invasion." (PMID 27713911, 2016). "Despite the established pro‐tumorigenic roles of certain MMPs (e.g., MMP2, MMP9, and MT1‐MMP), recent studies have demonstrated that some MMPs such as MMP8 and MMP11 might act against tumor growth and metastasis." (PMID 27292876, 2016). "Matrix metalloproteinase-2 (MMP2) is important in tumorigenesis, angiogenesis and tumor invasion." (PMID 26923459, 2016). "Furthermore, statistical analysis showed a significant difference between the expressions of MMP-2 and MMP-7 in normal and tumor tissues (p = 0.0001)." (PMID 27429508, 2016). "Furthermore, Mmp2, Mmp9, and Mmp13 become upregulated in MMTV-PyMT tumors and are also involved in tumor growth and metastasis." (PMID 27542270, 2016). "This association may be attributed to the overexpression of several growth factors, MMP2 and VEGF, which are induced by Stat3 activation and subsequently promote tumor invasion and angiogenesis." (PMID 27460364, 2016). "We have evaluated aMMP2-SIP uptake using MMP2 knock-down models, as negative control in different tumor types with varying MMP2 expression and activity." (PMID 26923459, 2016). "In the past decade, many studies have demonstrated that over-expression of MMP2 and MMP9 plays a vital role in metastatic tumour cells, promoting tumour growth and angiogenesis in the tumour, thereby providing nutrition to the tumour through the newly generated vessels." (PMID 27447567, 2016). "Thus, we observed expression of matrix metalloproteinases (MMP)-1, MMP-2, MMP-3, and MMP-9 mainly in the nuclei of tumor cells, while for MMP-3 and MMP-9 the immunoreactivity was also present in the cytoplasm of tumor cells and in the amyloid deposits." (PMID 27871286, 2016). "In conclusion, our findings confirmed that MMP-2, MMP-7, and MMP-9 may take part in various morphological features of PDAC tumor." (PMID 27429508, 2016). "In summary, these results demonstrated that Huaier extract could inhibit the macrophages induced angiogenesis by decreasing expression of VEGF, MMP2 and MMP9, and thus inhibit the formation of new blood vessels in tumor." (PMID 26831282, 2016).
tumor (continued). "Therefore, the aim of this study was to compare the expressions of mRNA for metalloproteinases (MMP-2 and MMP-9) and type IV collagen in two different histological types of BCC (nodular and infiltrative) and in normal tissues from the tumor interface." (PMID 27406386, 2016). "Besides, matrix metalloproteinase (MMP)-2 (gelatinase A, 72 kDa) and MMP-9 (gelatinase B, 92 kDa) plays importantly in the process of tumor cell migration and invasion." (PMID 26848867, 2016). "Upregulated expression of MMP2 and MMP9 may additionally support invasiveness of the motile tumor cells." (PMID 27419629, 2016). "In addition to enhancing tumor invasion and metastasis directly, MMP-7 exerts indirect effects through the activation of MMP-2 and MMP-9." (PMID 27271600, 2016). "It has also been reported that ERK1/2 could regulate expression levels of MMP2 and MMP9 in cancer cells, which can degrade extracellular matrix to promote metastasis in tumor." (PMID 26701209, 2016). "Among the various MMPs, MMP-2 (gelatinase A) and MMP-9 (gelatinase B) may play a significant role in tumor progression and invasion in GCT." (PMID 26863138, 2016). "In conclusion, zingerone showed strong anti-angiogenic activity via the inhibition of MMP-2 and MMP-9 during tumor progression, suggesting that zingerone may be a potential therapeutic drug for human cancers." (PMID 27323807, 2016). "The release of MMP-2 and MMP-9 from tumor cells and surrounding cells, including endothelial cells, could enhance invasion and angiogenesis during tumor progression." (PMID 27323807, 2016). "Similarly, exosomes of ovarian cancer ascites contain MMP-2, MMP-9 and urokinase-type plasminogen activator (uPa), all of them able to degrade the ECM, facilitating invasion and dissemination of tumor cells." (PMID 26426054, 2015). "MMP-2, MMP-9, LOX, CXCR4, FN and p-FAK are involved in remodeling the tumor metastatic microenvironment, and whether miR-33b can regulate the metastatic microenvironment deserves further investigation." (PMID 25919570, 2015). "Through bioinformatics analysis and miRNA PCR array and tumor metastasis PCR array, PTEN, ETV4, COL4A2 and MMP2 were logically been speculated as miR-29b target genes." (PMID 26063204, 2015). "Secretion of MMP2, which shows strong proteolytic activity toward the ECM, enables cancer cells to gain increased motility, invade adjacent tissues and cross the endothelial barriers, consequently leading to tumor metastasis." (PMID 25557170, 2015). "Two members of the MMP family, MMP-2 and MMP-9, are necessary for tumor invasion and metastasis." (PMID 26512779, 2015). "MMP-2 (gelatinase A) and MMP-9 (gelatinase B), which degrades type IV collagen, the major structural component of basement membranes, are overexpressed in various malignant tumors and are known to play crucial roles in tumor migration and invasion." (PMID 25625511, 2015). "Inactivating the JNK pathway by expressing a dominant-negative form of JNK (basket, bsk), depleting Mmp2 (but not Mmp1) or expressing the tissue inhibitor of metalloprotease (timp) in EBs of Sox21a flies reduced tumour burden and growth towards the lumen." (PMID 26690827, 2015). "Additionally, XH had a potent effect on reducing the expressions of MMP-2 and MMP-9 in LoVo cells and 4T1 (mouse breast cancer) tumor-bearing mice." (PMID 26170886, 2015). "Thus, the communication between adipocytes and tumor cells increased IGFBP-2 secretion, activated MMP-2 in tumor cells and promoted the durable expression of MMP-2." (PMID 25747684, 2015). "We analyzed tumor invasive potential by performing western blot analysis on tumor tissue to determine the expression levels of vimentin, MMP-9 and both the pro-form and the proteolytically processed activated form of MMP-2." (PMID 26083629, 2015).
tumor (continued). "Accordingly, MMP2 and MMP9 may function in primary tumor growth, invasion, and colonization, facilitating SK-sNEDD4 cell metastasis to the lung." (PMID 25823820, 2015). "As a natural target of TIMPs, MMP-2 and MMP-9 play important roles in tumor invasiveness." (PMID 25883224, 2015). "MMP-2 and MMP-9 play an important role in tumor cell migration and invasion." (PMID 25927362, 2015). "Tumor invasion requires the secretion of proteolytic enzymes by tumor cells to break down the extracellular matrix (ECM) proteins (e.g., collagen, fibronectin and laminin), with the matrix metalloproteinases (MMPs) MMP-2 and MMP-9 playing a major role." (PMID 25874926, 2015). "Our results not only pointed out that PMS significantly restricted allograft tumor growth at the concentrations chosen, but also demonstrate that the inhibition effect of PMS on MMP9/MMP2 activity may contribute to its anti-tumor effects." (PMID 26674531, 2015). "We suggest that the anti-tumor properties of DATS may beneficial for the inhibition of metastasis by down-regulating the activities and expression of ERK/NF-κB /MMP-2/MMP-9." (PMID 25927362, 2015). "In addition to MMP2 and MMP9, we investigated the expression of MMP3, MMP11, MMP13 and MMP14 in tumour cells." (PMID 26284589, 2015). "Stress selectively increased MMP9 expression in tumor cells (~50-fold compared to non-stressed mice) while stress enhanced MMP2 expression in cells from the stromal compartment (>100-fold compared to non-stressed mice)." (PMID 26193320, 2015). "The critical step in tumor invasion and metastasis is reportedly the breakdown of the ECM, which requires activation of proteolytic enzymes such as MMPs, particularly MMP-2 and MMP-9, as elevated levels of these are well documented to indicate an invasive phenotype." (PMID 25605016, 2015). "In the present study, the LX-2 human HSC line, induced by tumor-CM from human HCC cells, exhibited phenotypic characteristics, including increased cell proliferation, secretion of MMP-2 and gene expression levels of α-SMA, collagen I and TIMP-1, which are also induced by CD147." (PMID 25738354, 2015). "The expression rates of AR, MMP-2 and MMP-9 in the HCC tissue were 76.67, 73.33 and 76.67%, respectively, all of which were significantly higher than those in the tissues adjacent to the tumor." (PMID 25667651, 2015). "Additionally, TGF-β and miR-210 induced CAF senescence promotes fibroblast MMP-2 secretion and tumor cell EMT, enhancing in vitro tumor cell invasion." (PMID 25734659, 2015). "Given that Vimentin, MMP2 and Fibronectin are well-known key players of the epithelial-mesenchymal transition (EMT) process in promoting tumor metastasis; our results indicated a pro-metastasis function of RIPK4 by promoting the EMT process in the progression of CSCC." (PMID 26148476, 2015). "In conclusion, considering markers from PA and MMP protease families that is critical in regulating tumor progression, our study reveals the greatest prognostic significance of PAI-2 among uPA, uPAR, PAI-1 and PAI-2 in the PA family and MMP-2 and MMP-9 in the MMP family." (PMID 26230665, 2015). "It is known that when endothelial cells are subjected to hypoxic conditions (low PO2) such as inside of a tumor mass, MMP2 expression is elevated, and its specific endogenous inhibitor TIMP-2 and the hypoxic conditions enhance MMP2-dependent endothelial cell migration." (PMID 25887757, 2015). "Moreover, OCT4B upregulated the expression of MMP2 and MMP9, which are known to promote tumor invasion." (PMID 25816351, 2015). "An important aspect of EMT is acquisition of higher migration and invasion capacities of tumor cells coupled with increased expression of proteolytic enzymes of the extracellular matrix (ECM) such as gelatinases A and B, MMP-9, MMP-2, and urokinase-type plasminogen activator (uPA)." (PMID 24900952, 2014). "The expression of MMP-2 and MMP-9 is used to assess the ability of tumor aggressiveness." (PMID 24797571, 2014).